CCT2 (chaperonin containing TCP1 subunit 2)
Diseases named in the same sentence as CCT2 in open-access papers (continued):
Sharing a sentence is not in itself a finding about the gene and the disease.
breast carcinoma (continued). "Additionally, compared with normal cells (MCF-10A), most breast cancer cells exhibited higher CCT2 expression, providing additional evidence for the oncogenic function of CCT2 in breast cancer." (PMID 39079960, 2024). "We initially investigated CCT2 expression in human breast cancer using publicly available datasets." (PMID 39079960, 2024). "Taken together, these findings indicate that CCT2 could be a readout for increased activity of the CCT complex, as our lab showed with breast cancer models, and has practical applications as a diagnostic indicator and therapeutic target in cancer." (PMID 36185250, 2022). "To confirm the trend of high CCT2 gene expression correlating with tumor progression observed in the bioinformatics data, we examined the prevalence of the CCT2 protein in normal breast tissue compared to breast cancer tissues." (PMID 35749519, 2022). "We next ran a pilot study to evaluate CCT2 protein levels in different stages of breast cancer." (PMID 35749519, 2022). "Similarly, one study reported that, in breast cancer, a high expression of CCT2 predicted its poor prognosis." (PMID 36119498, 2022). "To determine if the detection of CCT2 in breast cancer cells could be extended to other cancer cells, we spiked CRL5853 and CRL5903 SCLC cell lines into blood and performed CCT2 staining in the CSS platform." (PMID 35749519, 2022). "Interestingly, CCT2 expression was also an independent prognostic factor for breast cancer in multivariate analysis of METABRIC cohort after adjusting for age, AJCC stage, Grade, ER status, PR status, as well as HER2 status." (PMID 33869000, 2021). "In the present study, we assessed the CCT2 expression status and related biological process by characterizing transcriptome data across two comprehensive genomic databases including a total of 2,994 breast cancer samples." (PMID 33869000, 2021). "released in 2000, they illustrated that Pescadillo and chaperonin CCT2 were two presumptive autocrine/paracrine factors of potential function in the regulation of the growth of breast cancer cells, which were identified to be highly upregulated by E2 (17beta estradiol)." (PMID 33869000, 2021). "In summary, our results revealed that CCT2 might be involved in regulating cell cycle pathway, and independently predicted worse prognosis in breast cancer patients." (PMID 33869000, 2021). "Since CCT2 is located on chromosome 12q15, an amplicon frequently found in soft tissue cancers as well as breast cancer, CCT2 may have the basic characteristics of an oncogene." (PMID 33996588, 2021). "CCT2 positive breast cancer cells were more invasive and had a higher proliferative index." (PMID 34227253, 2021). "Our finding that overexpressing CCT2 promoted the proliferation of breast cancer and breast epithelial cells is among the first to demonstrate that an increase in cancer cell growth and upregulation of select CDKs as well as other CCT subunits resulted from overexpressing this single CCT subunit." (PMID 31964905, 2020). "CCT2 also has important functional links to cancer, including survival of breast cancer cells and negative survival associations in breast cancer, non-small cell lung cancer and diffuse intrinsic pontine glioma." (PMID 32635403, 2020). "Recent studies have found that CCT2 is critical for the survival of breast cancer patients, and is significantly higher in hepatocellular carcinoma, colon cancer, extrahepatic cholangiocarcinoma, gallbladder cancer, and gastric cancer than benign lesions and normal tissues." (PMID 32117430, 2019). "Or it could be used for the diagnosis of disease severity in cancers like breast cancer, in which levels of CCT2 correlated with disease progression, as we have previously demonstrated." (PMID 29299146, 2017). "We and others found that CCT2 was elevated in breast cancer as well as in gall bladder carcinoma." (PMID 29299146, 2017).
breast carcinoma (continued). "Moreover, a genomic region containing CCT2 was reported to be amplified in breast cancer, and further shown to be amplified and/or overexpressed in approximately 13% of human breast cancers analyzed as part of the Tumor Genome Atlas (TCGA) project." (PMID 29112949, 2017). "Therefore, we explored whether breast cancer cell exos-derived CCT2 regulated Ca2+ influx in CD4+ T cells." (PMID 39079960, 2024). "Moreover, we utilized the JAK2/STAT3-specific inhibitor WP1066 to determine whether activation of this pathway is essential for the CCT2-mediated progression of breast cancer cells." (PMID 39079960, 2024). "Furthermore, we discovered that CCT2 can be encapsulated within exosomes and transferred from breast cancer cells to CD4+ T cells, where it suppresses CD4+ T cell activation by downregulating CD40L expression, thereby promoting tumor immune evasion and progression." (PMID 39079960, 2024). "Notably, overexpression of CCT2 in breast cancer cells had the opposite effect." (PMID 39079960, 2024). "Results from this MBC cohort provided insight on the relationship between tumor-based CCT2 expression and shed epithelial CTCs in breast cancer, suggesting that CCT2 may perform better as a marker for CTCs than standard epithelial markers alone, which is further explored." (PMID 35749519, 2022). "Collectively, we found that CCT2 promotes breast cancer cell cycle progression through G1/S, in 2D, spheroid and 2D post 3D cultures; however, this effect could be cell type dependent and may involve different mechanisms depending on the cell’s genetic make-up." (PMID 33996588, 2021). "Moreover, CCT2 was overexpressed in more malignant grades and molecular subtypes of breast cancer." (PMID 33869000, 2021). "For example, CCT2, CCT3, CCT4, and CCT5 were increased in breast cancer cells and positively correlated with tumor progression." (PMID 40374617, 2025). "Here, we demonstrated that breast cancer derived shCCT2 exosomes promoted NFAT1 activation in CD4+ T cells, whereas CCT2 exosomes had the opposite effect." (PMID 39079960, 2024). "Remarkably, breast cancer cells overexpressing Trim21 exhibited accelerated degradation of the CCT2 protein upon treatment with CHX, implicating Trim21 in modulating CCT2 stability." (PMID 39079960, 2024). "Fascinatingly, the results of this study indicate that breast cancer derived shCCT2 exosomes promote the Ca2+ influx in CD4+ T cells, while CCT2 exosomes inhibit Ca2+ influx." (PMID 39079960, 2024). "The addition of an anti-CCT2 antibody to the CSS platform resulted in improved CTC image analysis and increased detection of rare breast cancer and SCLC cells spiked into blood, which was confirmed in a pilot study of blood from SCLC patients." (PMID 35749519, 2022). "Pulse-chase experiments with mammary carcinoma FM3A cells revealed that turnover rates of individual CCT subunits varied significantly, with CCT4 having the shortest half-life (∼4 h) and CCT2 the longest half-life (∼8 h)." (PMID 35602608, 2022). "According to our studies, three subunits of CCT complex – CCT1, CCT2 and CCT6A strongly correlated with survival of breast cancer patients." (PMID 31101846, 2019). "Analysis of the Gene Expression Omnibus series revealed consistently elevated CCT2 expression in human breast cancer tissues compared with normal breast tissues." (PMID 39079960, 2024). "A systematic analysis of protein half-lives in MCF-7 breast cancer cells found, in contrast, that CCT4 had the longest half-life (∼10.6 h), followed by CCT8, CCT7 and CCT2, with half-lives between 7–8 h, and CCT5 and CCT3 with the shortest half-lives of 4.6 and 2.5 h, respectively." (PMID 35602608, 2022).
breast carcinoma (continued). "To investigate a role for CCT2 in the regulation of the cell cycle, we expressed an exogenous CCT2-FLAG construct in T47D and MCF7 luminal A breast cancer cells and examined cell proliferation under conditions of two-dimensional (2D) monolayer and three-dimensional (3D) spheroid cultures." (PMID 33996588, 2021). "Herein, we showed that CCT2 expression can upregulate MYC and CCND1 gene expression and promote metastatic-like behavior in luminal A breast cancer cells that are typically less aggressive than the basal-like/TNBC subtypes usually associated with MYC amplification." (PMID 33996588, 2021). "We used these TNBC cells for CCT2 depletion because, unlike the luminal A breast cancer cells, these cells tend to express increased amounts of endogenous CCT2 and are amenable to depletion." (PMID 33996588, 2021). "Interestingly, patients overexpressing two identified HSPs – HSPA2 and DNAJC20 exhibited longer survival, whereas overexpression of other four HSPs – HSP90AA1, CCT1, CCT2, CCT6A resulted in unfavorable prognosis for breast cancer patients." (PMID 31101846, 2019). "In breast cancer, CCT1 and CCT2 may be upregulated by driver oncogenes that are responsible for tumorigenesis." (PMID 29299146, 2017). "CCT2 was recently identified as significantly depleted in an RNAi-based growth and viability screen, as well as copy number amplified and overexpressed in the SUM-52 breast cancer cell line." (PMID 29112949, 2017). "Likewise in breast cancer, CCT1 and CCT2 were part of HSP signature that could predict outcomes and help stratify patients for treatment." (PMID 35602608, 2022). "Our lab previously showed that CCT2 expression did not correlate with ER or PR status and therefore could be used with different types of breast cancer including TNBC." (PMID 35749519, 2022). "To determine whether tumor levels of CCT2 correlated with prognostic markers for breast cancer, we examined the MBC cohort for levels of CCT2 in the tumor tissue, tumor lineage markers, time of diagnosis, and the number of CTCs enumerated using standard epithelial markers." (PMID 35749519, 2022). "CCT itself could activate genes that drive cell cycling, since overexpression of CCT2 in luminal A breast cancer cells increased the gene expression of MYC and CCND1 that statistically correlated with CCT2, while depletion of CCT6A in an HCC cell line decreased levels of cyclin D." (PMID 35602608, 2022). "Through the Cancer Genome Atlas (TCGA) and Molecular Taxonomy of Breast Cancer International Consortium (METABRIC) databases, we systematically reviewed a total of 2,994 cases with transcriptome data and analyzed the functional annotation of CCT2 by Gene ontology and KEGG analysis." (PMID 33869000, 2021). "Moreover, we noted that CCT3 mRNA and protein in our study did not vary substantially between the lentiviral control and CCT2-FLAG overexpressing breast cancer cells." (PMID 33996588, 2021). "To this end, we found that CCT2 protein levels, but not CCT3 as example, varied among breast cancer cell lines, with highest levels of CCT2 in TNBC cells and lowest in luminal A types and non-transformed breast epithelial cells (CCT3 shown as a representative of other subunits)." (PMID 31964905, 2020). "Additionally, we found that the level of CCT2 was independent of hormone receptor status in breast cancer, suggesting that CCT2 expression could be upstream of tumor lineage-defining markers." (PMID 35749519, 2022). "To show that results from MCF10A cells were not cell specific, we generated two luminal A breast cancer cell lines, MCF7 and T47D, that stably expressed CCT2-FLAG." (PMID 31964905, 2020). "However, unlike neuroblastoma cells, these breast cancer cells had low levels of CCT that were closer to normal breast epithelial cells than metastatic cells; hence increasing CCT2 changed their phenotypic behavior." (PMID 36185250, 2022).
colorectal cancer (8 papers, 2017 to 2023). A primary or metastatic malignant neoplasm that affects the colon or rectum. "CCT2 can also regulate protein folding functions associated with hypoxia in colorectal cancer." (PMID 35372018, 2022). "CCT2 was essential for antagonizing Gli-1 ubiquitination in colorectal cancer, especially under the hypoxic condition." (PMID 37500615, 2023). "We also performed validation in the GEO dataset, which showed that CCT2 was highly expressed in colorectal cancer and less in thyroid cancer compared with normal tissue." (PMID 36119498, 2022). "A recent study in colorectal cancer identified CCT2 as a synthetic lethal partner to mutant KRAS, which was found to be dependent on mitochondrial translation for viability." (PMID 30578123, 2019). "A similar correlation was observed with CCT1 (TCP1) and CCT2 in both hepatocellular carcinoma and colonic carcinoma, as well as with CCT2 in colorectal carcinoma." (PMID 29299146, 2017). "It has been shown that, during hypoxia in colorectal cancer, hypoxia activates the hedgehog pathway, CCT2 helps protein folding by binding to the oncogenic protein gli1, and a high expression of CCT2 and glii-1 enhances tumor invasion and migration in vivo and in vitro." (PMID 36119498, 2022). "CCT2 was a vital determinant of survival in CRC (colorectal cancer) patients and could regulate the folding of Gli-1, a Hedgehog signaling factor in relation to hypoxia." (PMID 33815471, 2021).
colon cancer (7 papers, 2017 to 2024). "A univariate survival analysis of 19 genes revealed that only CCT2 was associated with colon cancer prognosis, and its low expression was associated with poor prognosis." (PMID 35372018, 2022). "CCT2 is highly expressed in colon cancer and lowly expressed in UC, and its low expression is associated with a poor prognostic ratio." (PMID 35372018, 2022). "Subsequently, we also examined the expression levels of CCT2 in colon cancer cells (HCT116), thyroid cancer cells (TPC-1), and normal cell lines (NCM460, Nthy–cri3-1)." (PMID 36119498, 2022). "The results showed that CCT2 was highly expressed in colon cancer cells and less expressed in thyroid cancer cells." (PMID 36119498, 2022). "Expression of TCP1 was upregulated in 93% of HCC patients and 76% of colon cancer patients, while CCT2 was overexpressed in 100% of HCC patients and 82% of colon cancer patients." (PMID 34676169, 2021). "While investigations into the expression and role of CCT2 in human malignancies are somewhat limited, upregulated CCT2 expression has been documented in various cancers, including neuroblastoma, colon cancer, and small cell lung cancer, and is correlated with an unfavorable prognosis." (PMID 39079960, 2024). "Furthermore, increased CCT2 expression was observed in several other cancers, including colon cancer (COAD), large B-cell lymphoma (DLBC), glioblastoma (GBM), pancreatic cancer (PAAD), thymoma (THYM), and uterine carcinosarcoma (UCS)." (PMID 39079960, 2024). "This study reveals, for the first time, that CCT2 may be a promoter of UC transformation into colon cancer and identifies new gene candidates that could be used as biomarkers or potential therapeutic targets." (PMID 35372018, 2022). "We also verified the correlation between CCT2 expression in colon cancer and immune genes." (PMID 36119498, 2022). "In this study, CCT2 expression showed an increasing trend in normal, UC, and colon cancer tissues." (PMID 35372018, 2022). "Significant differences were obtained in the expression of CCT2 in UC and colon cancer tissues." (PMID 35372018, 2022). "For instance, CCT1 and CCT2 are upregulated in patients with HCC and colonic cancer and correlate with tumor proliferation and poor prognosis." (PMID 33313411, 2020).
hepatocellular carcinoma (7 papers, 2017 to 2024). A malignant tumor that arises from hepatocytes. "For example, there is a significant difference in the expression of TCP1/CCT2/CCT3/CCT4/CCT5/CCT6A/CCT7/CCT8 in hepatocellular carcinoma." (PMID 37058032, 2023). "For instance, CCT8 regulates cell proliferation, migration and invasion in several tumors; CCT2 inhibition reduces cell migration in tubulin-binding agent-resistant tumors; and CCT3 supports cell proliferation in hepatocellular carcinoma." (PMID 33917510, 2021). "Different studies have previously linked expression levels of different CCT subunits in various cancers, such as CCT2 in prostate, breast and lung cancers and CCT3 in hepatocellular carcinoma (HCC)." (PMID 37667113, 2024). "Previous studies reported that the expression levels of different CCT subunits were upregulated in various cancers, such as CCT2 in prostate, breast, and lung cancers, CCT3 in hepatocellular carcinoma (HCC), and CCT8 in HCC and glioblastoma." (PMID 33815471, 2021).
Leber congenital amaurosis (7 papers, 2018 to 2025). Leber congenital amaurosis (LCA) is a retinal dystrophy defined by blindness and responses to electrophysiological stimulation (Ganzfeld electroretinogram (ERG)) below threshold, associated with severe visual impairment within the first year of life. "A compound heterozygous mutation in CCT2 (p.[Thr400Pro]; p.[Arg516His]) is causal for Leber congenital amaurosis." (PMID 38830954, 2024). "Mutations in ADSL result in the rare autosomal recessive disorder adenylosuccinate lyase deficiency, while CCT2 mutations evoke the rare disease Leber congenital amaurosis." (PMID 37905813, 2023). "The heterozygous double mutation T400P and R516H in subunit CCT2 is known to cause Leber congenital amaurosis (LCA), a hereditary congenital retinopathy." (PMID 37644231, 2023). "A mutation in CCT2 (T400P) has been found in Leber congenital amaurosis/LCA." (PMID 40693240, 2025). "Leber congenital amaurosis (LCA) is a leading cause of early-onset blindness in children, and CCT2 is one of the eight encoded proteins of chaperonin containing T-complex protein-1 (CCT)." (PMID 30050903, 2018). "Furthermore, it is associated with normal retinal development and mutations in the gene (cct2) encoding for the protein that has been associated with retinal pathology (Leber congenital amaurosis; LCA), a rare, inherited genetic eye disease causing severe vision loss from birth or early infancy." (PMID 41488750, 2025).
triple-negative breast carcinoma (6 papers, 2020 to 2023). An invasive breast carcinoma which is negative for expression of estrogen receptor (ER), progesterone receptor (PR), and human epidermal growth factor receptor 2 (HER2). "Depletion of CCT2 in triple-negative breast cancer (TNBC) cells prevented tumor growth in a murine syngeneic model and impaired the formation of tumor spheroids." (PMID 35602608, 2022). "CCT2 depletion in a syngeneic murine model of triple negative breast cancer (TNBC) prevented tumor growth." (PMID 31964905, 2020). "For example, overexpression of CCT2 could promote triple-negative breast cancer cell chemoresistance and cell migration and invasion via the AKT/GSK3β/β-catenin and XIAP/Survivin pathways." (PMID 37006287, 2023). "Besides, their study also represented that cells expressing higher CCT2 were more invasive and showed a higher proliferative index, and depletion of CCT2 in a syngeneic murine model of triple negative breast cancer (TNBC) had a potential to prevent tumor growth." (PMID 33869000, 2021). "Using two cancer cell lines [triple negative breast cancer (TNBC) and non-small cell lung cancer (NSCLC)] that highly expressed CCT2, depletion of this subunit decreased anti-apoptotic proteins like XIAP and inhibited phosphorylation of AKT and GSK3." (PMID 35602608, 2022).
glioblastoma (5 papers, 2021 to 2025). The most malignant astrocytic tumor (WHO grade IV). "Increased expression of CCT2, CCT6A, and CCT7 in EVs from cavitron ultrasonic surgical aspirators (CUSA) samples in glioblastoma patients correlated with poor patient prognosis." (PMID 35749519, 2022). "Moreover, studies with glioblastomas demonstrated CCT6A, CCT1, CCT2, and CCT7 subunits increased in the tumor tissue and tumor-derived extracellular vesicles, particularly CCT6A." (PMID 40374617, 2025).